RNU1-16P (RNA, U1 small nuclear 16, pseudogene)
Synonyms: U1.64
Gene: Small nuclear RNA gene on chromosome 13 (113,478,915 to 113,479,078, reverse strand). Ensembl gene ENSG00000202347.
Homologues: Orthologues: chimpanzee U1 (98% identical), macaque U1 (94% identical), mouse Gm25587 (83% identical), guinea pig U1 (74% identical). Paralogues in human: RNU1-1 (85% identical), RNU1-2 (85% identical), RNU1-27P (85% identical), RNU1-28P (85% identical), RNU1-3 (85% identical), RNU1-4 (85% identical), RNVU1-18 (85% identical), RNVU1-29 (85% identical), U1 (85% identical), RNVU1-28 (84% identical), RNVU1-31 (84% identical), RNVU1-7 (84% identical), and 133 more.